TFRC (transferrin receptor)
Diseases named in the same sentence as TFRC in open-access papers (continued):
Sharing a sentence is not in itself a finding about the gene and the disease.
anemia (continued). "One study of iron transport found that embryos of transferrin receptor-1 (TfR1) knockouts were not compatible with life due to severe anemia." (PMID 33302392, 2020). "STAT5 knockout mice exhibit severe anemia because the expression of the antiapoptotic genes Mcl-1 and Bcl-xL is deregulated, and the expression levels of iron regulatory protein 2 (IRP-2) and transferrin receptor 1 (CD71) are reduced." (PMID 25860801, 2015). "Only two studies included iron-specific biomarkers, such as serum iron, ferritin and transferrin receptor, but did not report mortality rates for different categories of ferritin, TfR, etc., and only one study provided information on anemia etiology." (PMID 25533005, 2014). "Similar to other chronic infections, distinguishing between anaemia due to inflammation and IDA in patients with tuberculosis is challenging since commonly used markers of iron status, such as ferritin and, to a lesser extent, soluble transferrin receptor, are influenced by inflammation." (PMID 40882649, 2025). "Since FTH1/FTL (ferritin) and TF (transferrin) are not sufficiently accurate, as they are both elevated in any anemia or inflammation process, the ferritin index (ratio of soluble TFRC to log ferritin) has been suggested as a more stable, reliable and sensitive marker." (PMID 35327526, 2022). "The combination of low transferrin saturation, high ferritin, normal transferrin receptor levels, and elevated CRP in these patients suggests anemia of chronic disease rather than classic IDA." (PMID 39863874, 2025). "First, certain parameters such as serum ferritin (SF), soluble transferrin receptor (sTfR), and total body iron (TBI) were not measured; the mild anemia status assessment would be more accurate with the measurement of these parameters." (PMID 34956084, 2021). "Our data can only provide indirect information on the etiology of anemia from hemoglobin and MCV, since no parameters of iron metabolism like ferritin, transferrin saturation, or soluble transferrin receptor were obtained by the registry." (PMID 29358946, 2017).
breast carcinoma (137 papers, 1997 to 2026). "Ferroptosis, a process involving TFRC, is closely linked to tumor cells and plays a significant role in breast cancer drug resistance." (PMID 39744692, 2025). "The increased demand for iron uptake in a variety of solid cancers leads to high expression of TFRC, such as esophageal squamous cell carcinoma, lung cancer, breast cancer and renal cell carcinoma, it is associated with unfavorable prognosis." (PMID 38602575, 2024). "In line with the reported association with Ki67 (MKI67), TFRC correlated with a set of genes associated with highest proliferation in breast cancer." (PMID 38117806, 2023). "The results demonstrated that ACO1, DPP4, HMOX1, and TFRC were significantly associated with breast cancer grades (all p < 0.05)." (PMID 35154262, 2021). "The decreased expression of the cellular iron exporter ferroportin and the increased expression of the iron importers transferrin receptor (TfR) and lipocalin 2 are associated with poor prognosis in breast cancer." (PMID 31597263, 2019). "In addition, TFRC overexpression can be associated with poor prognosis and is considered an effective prognostic marker in different types of cancer, such as esophageal squamous cell carcinoma, breast cancer, renal cell carcinoma, and hepatocellular carcinoma." (PMID 37644594, 2023). "Breast cancer cells exploit iron metabolism by overexpressing transferrin receptor 1 (TfR1), the key mediator of iron uptake, thereby enhancing intracellular iron levels to meet their high metabolic demands." (PMID 40486542, 2025). "The upregulation of TFRC in ADR-resistant breast cancer cells can activate ferroptosis, thereby reversing ADR resistance." (PMID 39744692, 2025). "Studies have shown that iron accumulation and iron regulatory proteins, including transferrin (Tf), transferrin receptor (TfR), and ferritin heavy chain (FtH), increased after radiation treatment in breast cancer." (PMID 40429897, 2025). "Breast cancer cells exhibit increased iron uptake through overexpression of transferrin receptor 1, leading to intracellular iron accumulation." (PMID 40486542, 2025). "Concurrently, transferrin (TFR) secreted by TANs binds to the transferrin receptor (TFRC) on breast cancer cells, activating iron-dependent signaling pathways." (PMID 40568594, 2025). "To assess the correlation between the levels of LASS2 and TFRC, we analysed 35 thyroid cancer, 30 breast cancer, and 38 HCC tumour tissues." (PMID 38419028, 2024). "The expression of TFRC is significantly upregulated in breast cancer and pancreatic cancer, and TFRC is correlated with the infiltrating abundance and immune response of some immune cells." (PMID 38602575, 2024). "GSH has been observed to be higher in TNBC compared to the luminal subtype, possibly due to the oestrogen‐mediated reduction of transferrin receptor (TFR) expression in breast cancer." (PMID 38140764, 2024). "Our results confirm the frequent overexpression of transferrin receptor in all clinical and pathological classes of breast cancer, but also show variability between patients and even individual cells within the same tumor." (PMID 38117806, 2023). "Iron uptake was inhibited in human breast cancer cells via transfection with transferrin receptor-1 shRNA." (PMID 37593220, 2023). "In breast cancer, biomaterials targeting transferrin receptor were tested in primary orthotopic tumors, where a 70% average prevalence of TfR expression is well established." (PMID 38117806, 2023). "Both the GENT2 and TCGA breast cancer data sets showed increased gene expression of TFRC (p<0.0001) in breast cancer (N = 5574 and N = 1210) relative to normal breast (N = 475 and N = 113 respectively)." (PMID 38117806, 2023). "TFRC gene and protein expression were high in breast cancer of all subtypes and stages, and in 60–85% of bone metastases." (PMID 38117806, 2023).
breast carcinoma (continued). "A wide survey shows high expression of transferrin receptor not only in primary breast tumors, but also in refractory/relapsing breast cancer and its visceral and bone metastases." (PMID 38117806, 2023). "Our previous study also indicated that TFRC expression was closely and positively correlated with the infiltration levels of many immune cells in breast cancer." (PMID 35847985, 2022). "HFn is specifically recognized by transferrin receptor 1 (TfR1), which is overexpressed in several human breast cancers including 4T1 and MDA-MB-231, and promotes the intracellularization of these nanoparticles." (PMID 35363115, 2022). "The heat map shows the significant correlations between ERO1 and PERK, EIF2 alpha, VEGFA, SERPINE1, PLAU, TFRC and MMP1 in basal tumors, confirming the strong association of ERO1 with the PERK branch of UPR and angiogenesis in basal breast cancer." (PMID 33531624, 2021). "For example, reduction in the expression of FPN, high ferritin, hepcidin, transferrin receptor (TfR1; CD71) expression, and high labile iron content (LIP) are consistent with the findings associated with breast cancer." (PMID 34820382, 2021). "Shpyleva et al43 found a high abundance of TFRC in breast cancer, and TFRC antibodies have been used to inhibit tumour growth." (PMID 33626208, 2021). "Fluvastatin enhanced iNOS expression, NO production, and nitrite levels in breast cancer cells, while reduced transferrin receptor (Tfr1) expression and iron uptake leading to cell death." (PMID 34502450, 2021). "The 17β-oestradiol can upregulate TFRC in ER+ breast cancer cells, and a high-17β-oestradiol and high-iron environment can promote the proliferation of breast cancer cells." (PMID 33292585, 2020). "In fact, the presence of transferrin receptor (TfR) on the surface of the breast cancer cells facilitated the specific binding affinity of the nanomicelles through T7." (PMID 32547709, 2020). "In our study, the gene expression of the transferrin receptor and iron transporter in breast cancer cells was significantly upregulated, and cellular ROS and cellular lipid peroxidation were intensified." (PMID 33294119, 2020). "Expression of TFRC regulated intracellular total iron and proliferation and invasion of the breast cancer cells in vitro and in vivo." (PMID 33292585, 2020). "Transferrin receptor expression is increased in breast cancer tissues confirming previous observations." (PMID 28216608, 2017). "For example, breast cancer patient microarray data demonstrate that increased transferrin receptor expression or decreased ferroportin expression in breast tumors are associated with poor prognosis." (PMID 28270217, 2017). "Human breast cancer MDA-MB-231 cells were transfected with transferrin receptor-1 (TfR1) shRNA to constitutively impair iron uptake." (PMID 20723262, 2010). "MiR-320 expression level was down-regulated in primary breast cancer (BC), and inhibited HL-60 cell proliferation by targets transferrin receptor 1 (CD71)." (PMID 20386663, 2010). "Indeed, transferrin receptor (TfR), a membrane protein involved in iron metabolism, has been shown to be upregulated in breast cancer compared to normal breast or fibromas." (PMID 40141347, 2025). "Breast cancer cells exploit iron for increased proliferation by enhancing iron uptake through transferrin receptor overexpression, suppressing iron export via ferroportin downregulation, and utilizing iron storage proteins such as ferritin to prevent oxidative damage." (PMID 40486542, 2025). "T7‐MNTs target lysosomes via the transferrin receptor‐mediated endocytosis in breast cancer cells." (PMID 38095513, 2024). "The tyrosine kinase inhibitor lapatinib is a commonly used chemotherapy drug for HER-2+ breast cancer patients, which can induce iron accumulation and ferroptosis by increasing the expression of transferrin receptor 1 (TFR1) in cancer cells, inhibiting brain metastasis of cancer tissues." (PMID 39664391, 2024).
breast carcinoma (continued). "Our data showed that LASS2 overexpression promotes iron uptake by upregulating TFRC expression in thyroid and breast cancer cell lines while simultaneously reducing iron storage by downregulating FTL and FTH expression, thereby elevating labile iron, which further confers ferroptosis sensitivity." (PMID 38419028, 2024). "Former investigation suggested that circ-TFRC was abnormally expressed in breast cancer (BC)." (PMID 38678242, 2024). "Similarly, in the GSE43837 dataset, TFRC was expressed at comparable levels between primary breast cancer and brain metastases." (PMID 38117806, 2023). "Upregulated expression of TFRC was markedly correlated with a poor prognosis for patients with breast cancer, indicating that TFRC may be an independent prognostic marker for breast cancer." (PMID 36237302, 2022). "Moreover, the expression of LAG3, CTLA-4, PD-L1, CD274, TIGIT, HAVCR2 and PDCD1LG2 was upregulated in the TFRC high-expression group compared with the TFRC low-expression group in breast cancer." (PMID 35847985, 2022). "Moreover, it was reported that transferrin receptors (TFRC) played the important role in varieties of tumors, such as epithelial ovarian cancer, breast cancer, and liver cancer." (PMID 34362387, 2021). "This suggests that especially changes in haptoglobin, but also fibrinogen beta chain, thrombospondin-4 and transferrin receptor protein 1 is indicative of metastasis, at least in this breast cancer model, and should be further evaluated as general breast cancer biomarkers." (PMID 31042781, 2019). "Increased Levels of transferrin receptor expression in cancer cells, such as epithelial cancer cells, cervical cancer cells, and breast cancer has been observed to provide more amount of available iron because iron is essential for cell proliferation and spread of cancer." (PMID 26664465, 2015). "The nanobioconjugate carries anti-tumor nucleosome-specific monoclonal antibody (mAb) 2C5 to target breast cancer cells, anti-mouse transferrin receptor (TfR) antibody for drug delivery through the host endothelial system, and Morpholino antisense oligonucleotide (AON) to inhibit EGFR synthesis." (PMID 22355336, 2012). "• Have a higher risk of breast cancer and CRC.• Increased affinity of transferrin receptor (TFR) for transferrin followed by increased cellular uptake of iron through complexes of the wild-type HFE gene product with the transferrin receptor and two HFE mutants (Cys282Tyr, His63Asp) may occur." (PMID 40066098, 2025). "Importantly, by analysing the average optical density values, we confirmed that the LASS2 protein level was positively correlated with the TFRC protein level in thyroid and breast cancer tissues but negatively correlated with the TFRC protein level in HCC tissues." (PMID 38419028, 2024). "Consistent with this notion, it has been reported that ERα can negatively regulate the level of transferrin receptor TFRC, enhancing the resistance of ER+ breast cancer cells to ferroptosis." (PMID 39833180, 2025). "Experimental results demonstrate that HTI-NPs can increase the expression of TFRC in MCF-7/ADR cells, induce ROS production in cells, and selectively kill drug-resistant breast cancer cells." (PMID 39507754, 2024). "In this study, we set out to characterize gene and protein expression of transferrin receptor (TfR, TFRC) of breast cancer broadly and systematically." (PMID 38117806, 2023). "Another study used a transferrin receptor aptamer (TRA) to deliver miR-126 to endothelial cells and breast cancer." (PMID 35269947, 2022). "The transferrin receptor (TFR), for example, is overexpressed in numerous tumor cells, most notably in breast cancer." (PMID 32932957, 2020). "Transferrin, TFRC and SLC11A2, which are responsible for importing iron into cells, are also expressed at higher levels in breast carcinoma than normal tissues, while the iron exporter SLC4A1 exhibited lower expression." (PMID 33292585, 2020).
breast carcinoma (continued). "The specific active target overexpressed receptors for breast cancer cells include human epidermal receptor (HER), folate receptor, transferrin receptor and glycoproteins." (PMID 32547709, 2020). "The TFRC and RPLP0 identified by us have been previously reported as reference genes in other cell types, including dexamethasone-exposed breast cancer cells and CD19-positive chronic lymphocytic leukemia cells." (PMID 25193495, 2014). "Since TFRC expression is promoted by the Akt/mTOR pathway, this finding is in line with lapatinib-mediated Akt inhibition in HER2-overxpressing breast cancer cells." (PMID 20126311, 2010). "Another important finding is that some of the commonly used control genes in breast cancer (ACTB and TFRC) appear to be less stable than previously assumed." (PMID 19187545, 2009). "CD71, a transferrin receptor, is an important mediator of ferroptosis, and its degradation, mediated by NEDD4L via the ubiquitin–proteasome system, inhibits ferroptosis in breast cancer cells after exposure to ionizing radiation." (PMID 38027016, 2023). "Consequently, we identified five putative breast cancer RNA-binding proteins (PUF60, TFRC, KPNB1, NSF, and SF3A3) showing strong tumorigenic characteristics." (PMID 35453681, 2022). "Transferrin receptor 1 (TFR1), an independent prognostic factor, is positively related to the amounts of immune cells (CD8+ T cells, CD4+ T cells, neutrophils, B cells, macrophages, and dendritic cells) in breast cancer patients." (PMID 36467032, 2022). "Thus, based on their tumorigenic characteristics presented in this study and their roles in other cancer types, we identified five new putative breast cancer RBPs: PUF60, TFRC, KPNB1, NSF, and SF3A3." (PMID 35453681, 2022). "Of note, the authors also showed a high expression level of TFRC in carcinoma tissues of patients with HER2+ breast cancer, but the regulatory machinery was not demonstrated in the study." (PMID 33292585, 2020). "Luminal C subtype, characterized by molecular profiling and unrecognizable via IHC displays the overexpression of genes that are characteristic for non-luminal breast cancers, like transferrin receptor (CD71), MYB, nuclear protein P40, SQLE, and GGH." (PMID 30382472, 2019). "Delivery of zinc via transferrin receptor and by ZIP7 activation may thus synergistically promote a more aggressive, endocrine resistant phenotype of breast cancer." (PMID 31483418, 2019). "Surprisingly, neither overexpression nor knockdown of DCYTB affected levels of ferritin H, transferrin receptor, labile iron or total cellular iron in breast cancer cells." (PMID 28270217, 2017). "TFRC and ACTB were verified as the best combination of two genes for breast cancer quantification." (PMID 21702980, 2011). "According to studies, the expression of the transferrin receptor (TfR) is up to five times higher in cancerous tissue than in healthy tissue, DOX-Tf compound should be able to increase the intracellular concentration of medicines in breast cancer cells, assisting in the treatment of chemoresistance." (PMID 36970353, 2023). "On the basis of our findings, we suggest that TFRC is the most stable EC, ACTB and TFRC is the best combination of two reference genes to quantify uPA, and that using RPLP0 and GAPDH are not recommendable for breast cancer." (PMID 21702980, 2011). "Similarly, we found a negative correlation between the TFRC protein level and the clinical TNM stage in breast cancer (P = 0.015)." (PMID 38419028, 2024).